LPAR1 (lysophosphatidic acid receptor 1)
Description:
Receptor for lysophosphatidic acid (LPA). Plays a role in the reorganization of the actin cytoskeleton, cell migration, differentiation and proliferation, and thereby contributes to the responses to tissue damage and infectious agents. Activates downstream signaling cascades via the G(i)/G(o), G(12)/G(13), and G(q) families of heteromeric G proteins. Signaling inhibits adenylyl cyclase activity and decreases cellular cAMP levels. Signaling triggers an increase of cytoplasmic Ca(2+) levels. Activates RALA; this leads to the activation of phospholipase C (PLC) and the formation of inositol 1,4,5-trisphosphate. Signaling mediates activation of down-stream MAP kinases (By similarity). Contributes to the regulation of cell shape. Promotes Rho-dependent reorganization of the actin cytoskeleton in neuronal cells and neurite retraction. Promotes the activation of Rho and the formation of actin stress fibers. Promotes formation of lamellipodia at the leading edge of migrating cells via activation of RAC1 (By similarity). Through its function as LPA receptor, plays a role in chemotaxis and cell migration, including responses to injury and wounding. Plays a role in triggering inflammation in response to bacterial lipopolysaccharide (LPS) via its interaction with CD14. Promotes cell proliferation in response to LPA (By similarity). Inhibits the intracellular ciliogenesis pathway in response to LPA and through AKT1 activation. Required for normal skeleton development. May play a role in osteoblast differentiation. Required for normal brain development. Required for normal proliferation, survival and maturation of newly formed neurons in the adult dentate gyrus. Plays a role in pain perception and in the initiation of neuropathic pain (By similarity).
Synonyms: EDG2; LPA1; edg-2; rec.1.3; vzg-1; Gpcr26; Mrec1.3; VZG1
Tractability: Small molecule: a drug acting on it is in phase 2 or 3 trials; a structure with a bound ligand is known; a high-quality ligand is known; it belongs to a druggable protein family. Antibody: UniProt places it where antibodies can reach, with high confidence; its Gene Ontology location is reachable by antibodies, with high confidence; UniProt predicts a signal peptide or a membrane-spanning region. PROTAC: a small molecule that binds it is known.
Target class: EDG receptor; Family A G protein-coupled receptor; Lipid-like ligand receptor (family A GPCR); Membrane receptor; Small molecule receptor (family A GPCR)
Chemical probes: AM095
Gene: Protein-coding gene on chromosome 9 (110,871,773 to 111,038,863, reverse strand). Ensembl gene ENSG00000198121.
Subcellular location: Cell surface; Cell membrane; Endosome
Pathways (Reactome):
Signal Transduction: G alpha (i) signalling events; G alpha (q) signalling events; Lysosphingolipid and LPA receptors
Gene Ontology:
Molecular function: lysophosphatidic acid binding; lysophosphatidic acid receptor activity; protein binding; G protein-coupled receptor activity; G-protein alpha-subunit binding; lipid binding; PDZ domain binding; phospholipid binding
Biological process: cell chemotaxis; G protein-coupled receptor signaling pathway; negative regulation of cilium assembly; phospholipase C-activating G protein-coupled receptor signaling pathway; positive regulation of canonical NF-kappaB signal transduction; adenylate cyclase-activating G protein-coupled receptor signaling pathway; adenylate cyclase-inhibiting G protein-coupled receptor signaling pathway; negative regulation of neuron projection development; neurogenesis; positive regulation of cytosolic calcium ion concentration; positive regulation of MAPK cascade; positive regulation of Rho protein signal transduction; positive regulation of stress fiber assembly; regulation of cell shape; cellular response to 1-oleoyl-sn-glycerol 3-phosphate; cellular response to oxygen levels; cerebellum development; corpus callosum development; myelination; negative regulation of cAMP/PKA signal transduction; oligodendrocyte development; optic nerve development; positive regulation of apoptotic process; positive regulation of dendritic spine development; positive regulation of smooth muscle cell chemotaxis; and 2 more
Cellular component: cell surface; endocytic vesicle; endosome; plasma membrane; cytoplasm; dendritic shaft; dendritic spine; GABA-ergic synapse; glutamatergic synapse; membrane; neuronal cell body; postsynaptic membrane; presynaptic membrane
Genetic constraint (gnomAD): Loss-of-function variants: 4 observed, 23.53 expected, observed/expected ratio (o/e) 0.17, 90% interval 0.083 to 0.39. The upper end of that interval is the gene's LOEUF score, 0.39, which puts it in group 1 of 6, group 1 being the genes least tolerant of losing a copy. Missense variants: 308 observed, 505.88 expected, observed/expected ratio (o/e) 0.61, 90% interval 0.55 to 0.67. Synonymous variants: 159 observed, 173.41 expected, observed/expected ratio (o/e) 0.92, 90% interval 0.81 to 1.05.
Homologues: Orthologues: macaque LPAR1 (99% identical), dog LPAR1 (97% identical), mouse Lpar1 (97% identical), rat Lpar1 (97% identical), chimpanzee LPAR1 (97% identical), guinea pig LPAR1 (97% identical), rabbit LPAR1 (95% identical), tropical clawed frog lpar1 (91% identical), zebrafish lpar1 (66% identical). Paralogues in human: LPAR2 (49% identical), LPAR3 (46% identical), S1PR1 (34% identical), S1PR3 (32% identical), S1PR4 (30% identical), S1PR5 (30% identical), S1PR2 (28% identical), CNR1 (26% identical), MC5R (23% identical), GPR12 (23% identical), MC3R (23% identical), GPR6 (22% identical), and 6 more.
Diseases named in the same sentence as LPAR1 in open-access papers:
LPAR1 is named in the same sentence as 164 diseases in open-access papers, as found by Europe PMC text mining. Sharing a sentence is not in itself a finding about the gene and the disease. The quoted sentences say what the papers report.
breast carcinoma (49 papers, 2004 to 2025). "Thereby, LPAR1–3 have been implicated in various aspects of breast cancer progression, including proliferation, migration, invasion, and metastasis." (PMID 39338222, 2024). "Targeting of the lysophosphatidic acid receptor 1 (LPA1) gene that has been implicated in promoting metastasis, via the specific inhibitor Debio-0719, was shown to induce dormancy at the secondary tumor site in a breast cancer model." (PMID 31817646, 2019). "The lysophosphatidic acid receptor 1 (LPA1) inhibitor Debio-0719 induces breast cancer dormancy by reducing proliferative markers such as Ki67 and ERK, while increasing the growth inhibiting pathway p38." (PMID 39682769, 2024). "Clinically, they measured the HB-EGF and LPAR1 levels through q-PCR in the primary tumors of 234 breast cancer patients who participated in a cohort study, and also found that their breast tumors significantly expressed high levels of HB-EGF." (PMID 35814375, 2022). "A previous study described how LPAR1 plays a key role in tissue fibrosis and carcinogenesis 57 and modulates metastasis in basal breast cancer by activating the LPA1/ZEB1/miR-21 pathway." (PMID 34104083, 2021). "Aberrant LPAR1 expressions were observed in many cancer cell lines and primary tumors, including ovarian cancer, breast cancer, liver cancer, gastric cancer, pancreatic cancer, lung cancer, glioblastoma (GBM), and osteosarcoma." (PMID 34209775, 2021). "It has been reported that breast cancer cells express elevated levels of LPAR1, LPAR2, and LPAR3 and that these LPA receptors are involved in stimulating tumorigenic and metastatic cascades via Wnt, MAPK, and PI3K pathways." (PMID 34440828, 2021). "The association between LPAR1 and tumor-infiltrating immune cells in multiple cancer types was based on the TIMER database, including breast cancer, head and neck cancer, colorectal cancer, kidney cancer, and prostate cancer." (PMID 32656075, 2020). "Examples of this include, the bioactive lipid, lysophosphatidic acid, and its receptor, LPAR-1 in breast cancer, chemokines, CXCL8/IL8 and CXCR1 and CXCR2 in melanoma, pancreatic cancer and gastric tumors and CXCL12 and CXCR4 in multiple cancers." (PMID 33329395, 2020). "In brief, LPAR1 was downregulated in colorectal cancer, breast cancer, kidney cancer, head and neck cancer, and prostate cancer based on the Oncomine database and TCGA." (PMID 32656075, 2020). "LPAR1 plays as an important role in the development of malignant tumors, including breast cancer, ovarian cancer, and pancreatic cancer, by binding to LPA and activating downstream targets." (PMID 31384176, 2019). "Scatter plot analysis for LPAR1 and ZEB1 correlation in the non basal and basal breast cancer cell lines highlights the fact that LPAR1 and ZEB1 expression correlates significantly in the basal but not in the non-basal subtypes." (PMID 26098771, 2015). "We observed that 54.16% of the basal breast cancer cell lines expressed LPAR1 and 37.5% expressed ZEB1 above the overall means." (PMID 26098771, 2015). "The strong correlation between ZEB1 and LPAR1 was most prominent in primary tumors of patients with basal breast cancers." (PMID 26098771, 2015). "Based on the quantification of HB-EGF in vitro, our results demonstrated that the treatment of MDA-MB-231 breast and PC3 prostate cancer cells with LPA1–3 antagonists (Ki16425, Debio0719) mimicked Lpar1 gene silencing in MDA-B02 breast cancer cells." (PMID 24828490, 2014). "LPAR1 has been found to induce migration in cells from breast cancer, pancreatic cancer, and hepatocellular carcinoma while it inhibited metastasis and invasion in prostate organotypic models." (PMID 24928086, 2014). "Other studies from breast cancer cell lines indicated that both LPAR1 and LPAR2 mediated LPA-induced chemotaxis in breast carcinoma cells." (PMID 24744506, 2014). "Particularly LPAR1–3 expression has been detected in breast cancer tissues." (PMID 39338222, 2024).
breast carcinoma (continued). "In addition, LPA/LPAR1 signaling in basal breast cancers increases the expression of various miRNAs, including miR-21." (PMID 37373116, 2023). "Finally, their results showed a new LPA-induced molecular pathway that targets LPAR1 in basal breast cancer patients." (PMID 35814375, 2022). "Especially LPAR1–3 were identified in a variety of breast cancer cell lines to promote proliferation, migration, and invasion and might participate in the initiation of breast cancer." (PMID 35365723, 2022). "LPAR1–3 play a crucial role in breast cancer (reviewed by4)." (PMID 35365723, 2022). "Dormancy could further be promoted in experimental breast cancer models via the inhibition of lysophosphatidic acid receptor 1 (LPA1), which induces a p38high/ERKlow state." (PMID 35837334, 2022). "Likewise, Peyruchaud and coworkers demonstrated that inhibition of LPAR1 or ATX substantially blocked breast cancer bone metastasis." (PMID 36080255, 2022). "Therefore, Lyso-PEs induce Ca2+ flux signaling by using lysophosphatidic acid receptor 1 (LPAR1) in breast cancer cells." (PMID 35409331, 2022). "Proliferation and/or motility of cancer cells were promoted after LPA signalling through the LPAR1 in colon, gastric, and breast cancer, LPAR2 in colon and renal cancer, LPAR3 in colon, pancreatic, and breast cancer, LPAR4 in fibrosarcoma, and LPAR6 in hepatic and pancreatic cancer." (PMID 34722305, 2021). "Indeed, LPAR1 is crucial in bone metastasis of breast carcinoma, LPAR2 promotes colorectal cancer and aggressiveness of ovarian cancer cells, whereas LPAR3 enhances migration of hepatoma cells (and refer therein)." (PMID 31652837, 2019). "The current report examined the extent of metastasis-induced fibrosis in breast cancer model systems, and tested the metastasis preventive efficacy and fibrosis attenuation of antagonists for LPAR1 and Idiopathic Pulmonary Fibrosis (IPF) in breast and ovarian cancer models." (PMID 29805748, 2018). "Finally we analyzed whether LPAR1 levels might have an impact on metastasis recurrence in basal breast cancers." (PMID 26098771, 2015). "In the present study, we did not observe a significant increase or decrease in mRNA expression of LPAR1, LPAR3, and LPAR6 RNA in breast cancer cells after irradiation." (PMID 39338222, 2024). "The effects of irradiation on the mRNA expression of LPAR1–3 and LPAR 6 were analyzed at 48 h after irradiation for the different breast cancer cell lines." (PMID 39338222, 2024). "The lysophosphatidic acid receptor 1 (LPA1), another lipid receptor, is overexpressed in breast carcinoma and increases metastasis." (PMID 37071417, 2023). "Even though LPA is the cognate agonist of six different GPCRs; in oncogenic settings, LPA receptor 1 (LPAR1) has been highlighted as the main promoters of metastatic dissemination of lung, ovarian, pancreatic, melanoma, and breast cancer cells, among others." (PMID 34808208, 2022). "The ATX-LPAR axis is also upregulated in CSC and the inhibition of ATX and LPAR1 attenuates the CSC-like characteristics of ovarian and breast cancers." (PMID 36080255, 2022). "ATX, LPAR1 and LPAR2 are overexpressed in different tumor types, including ovarian cancer, osteocarcinoma, metastatic melanoma, neuroblastoma, breast cancer, pancreatic cancer, prostate cancer, and hepatocellular carcinoma." (PMID 36080255, 2022). "Many groups have reported that expression levels of LPA receptors (LPAR1, LPAR2, and LPAR3) and/or β-arrestins are elevated in advanced stages of breast cancers." (PMID 34440828, 2021). "Regarding specific receptors, overexpression of LPAR1 and LPAR2 has been observed across breast cancers, as reported by several research groups." (PMID 34440828, 2021). "Expression of human ATX, LPAR1, LPAR2 or LPAR3 in transgenic mice is sufficient to induce late-onset mammary carcinomas." (PMID 31652837, 2019). "Two orally available LPAR1 antagonists, SAR100842 and EPGN9878, significantly inhibited breast cancer motility to LPA in vitro." (PMID 29805748, 2018).
breast carcinoma (continued). "In transgenic mouse models, overexpression of each of these individual LPA receptors (LPAR1, LPAR2 and LPAR3) under the control of the mouse mammary tumour virus long terminal repeat (MMTV-LTR) promoter led to the formation of late-onset mammary carcinomas." (PMID 25572802, 2015). "We then extracted the LPAR1 and ZEB1 expression data from 51 human breast cancer cell lines from the publically available database GSE12777, classified into basal (n = 24) and non basal subtypes (n = 27)." (PMID 26098771, 2015). "LPAR1/miR-21, ZEB1/miR-21 and LPAR1/ZEB1 pairwise correlations were determined using data from in three publically available human breast cancer databases containing both mRNA and microRNA data (GSE5460; GSE16391; GSE12276)." (PMID 26098771, 2015). "Other studies have found that lysophosphatidic acid receptor 1 (LPA1), a metastasis-driving GPCR, upregulates oncogenic miR-21 via PI3K/ZEB1 to promote breast cancer invasion and bone colonization; miR-21 inhibition blocks LPA1-mediated migration and reduces metastatic burden in vivo." (PMID 41230330, 2025). "Differentially expressed genes, especially those in five modules, including OAS1, IFI27, LPAR1, PTGFR, ITGB4, and ITGA6, might participate in the epithelial-mesenchymal transition process in breast cancer cell line DKTA." (PMID 36289533, 2022). "A more potent dual LPAR1/3 antagonist, Debio-0719, was found to reduce pulmonary and bone metastases of murine 4T1 breast cancer cells without affecting primary tumor size." (PMID 34209775, 2021). "A particularly important study by Liu and colleagues showed that overexpression of LPAR1, LPAR2, or LPAR3 in transgenic mice could induce mammary tumors." (PMID 34440828, 2021). "Beside a strong significant correlation between high levels of LPAR1 mRNA and the lymph node status from an unselected breast cancer population, we previously found that LPAR1 levels did not predict metastasis recurrence." (PMID 26098771, 2015). "In contrast, only 11.1% of the non basal breast cancer cell lines expressed LPAR1 and none expressed ZEB1 above the corresponding overall means." (PMID 26098771, 2015). "In this study we demonstrated that in human breast tumors there was a significant positive correlation between LPAR1, ZEB1 and miR-21 and that in basal breast cancer cell lines ZEB1 regulates LPA-induced miR-21 expression through an LPA1/PI3K dependent mechanism." (PMID 26098771, 2015). "In this context, breast cancer cells that overexpress LPAR1 do not express ATX." (PMID 36080255, 2022). "Here, based on the sub-classification of human breast tumors from publically available databases, we found for the first time that as opposed to non-basal breast cancer patients, expression levels of LPAR1 predicted lung metastasis-free survival in TNBC patients." (PMID 26098771, 2015). "As opposed to LPAR1, we did not observe significant correlations between ZEB1 and LPAR2 or LPAR3 in publicly available breast cancer cell line databases." (PMID 26098771, 2015). "Moreover, in addition to a higher prevalence of LPA1 expression in basal than in non-basal breast cancer cell lines, there was a significant correlation between ZEB1 and LPAR1 in cell line of basal subtypes but not of non-basal subtype." (PMID 26098771, 2015).